TRPV2 (transient receptor potential cation channel subfamily V member 2)
Diseases named in the same sentence as TRPV2 in open-access papers (continued):
Sharing a sentence is not in itself a finding about the gene and the disease.
tumor (continued). "Indeed, we found the expression level of β-catenin was significantly down-regulated in immunocompetent xenograft models by TRPV2-PCNH-guided phototherapy, suggesting this treatment may transition the tumour microenvironment to a less resistant milieu." (PMID 32807785, 2020). "Moreover, in western blotting and IHC analyses of HT-29-TRPV2 tumour tissues, expression of both non-phospho and total β-catenin were down-regulated only in mice treated with TRPV2-targeted phototherapy." (PMID 32807785, 2020). "Moreover, the loss of TRPM3, TRPV1, TRPV2, and TRPML1 expression has been proposed as a negative prognostic marker for GBM patients, because of their significant and progressive down-regulation as the tumor grade increases." (PMID 33928077, 2021). "Tranilast, a TRPV2 inhibitor, at 50 μM, suppress OSCC stem cells, generated from ALDH1A1-positive OSCC TE8 cells, more than non-CSC and decreases tumor sphere numbers." (PMID 31801263, 2019). "We previously demonstrated the anticancer effect of Tranilast against EC by antagonizing TRPV2, which is responsible for promoting EC tumorigenesis via the HSP70/27 and PI3K/Akt/mTOR pathways; the result also showed no off-target cytotoxicity, especially against non-tumor cells and tissues." (PMID 38336680, 2024).
infection (9 papers, 2014 to 2025). The state of being infected such as from the introduction of a foreign agent such as serum, vaccine, antigenic substance or organism. "Infection with Ad-TRPV2 increased TRPV2 expression approximately twofold, whereas Ad-Cre infection reduced expression to ~15% of the control level (original data-3)." (PMID 41397955, 2025). "Taken together, these results demonstrated that rigid zone formation at the plasma membrane potentiate TRPV2 activity and showed the importance of TRPV2 recruitment in lipid rafts to mediate calcium influx upon infection." (PMID 29523858, 2018). "Treatment of macrophages with LPS from P. aeruginosa gave the same results further supporting the fact that TRPV2 is recruited in lipid rafts during infection." (PMID 29523858, 2018). "As expected, after 10 min infection with P. aeruginosa and 30 min biotinylation, a significant increase of the presence of TRPV2 at plasma membrane was observed." (PMID 29523858, 2018). "Trpv2 is also modulated by inflammatory molecules, because systemic infection induces an increase in Trpv2 expression in the rat dorsal root ganglion." (PMID 24505289, 2014). "We next examined how knockout of TRPV2 affected the early infection process." (PMID 36261399, 2022). "The ability of TRPV2 to promote LPS-dependent NF-κB activation also mirrors our finding during EPEC-1 and EPEC-1-TirAA infection." (PMID 33378358, 2020). "One hundred fifty-seven differentially expressed cellular proteins were identified, including 84 upregulated and 73 downregulated proteins at 48 h post-infection, among which CXCL8, DDX3X, and TRPV2 may play crucial roles in viral propagation." (PMID 39772141, 2024). "In summary, our data indicate that febrile temperatures promote cytokine secretion through SARS-CoV-2 S-mediated infection, and that knockdown or inhibition (SKF-96365) of TRPV2 significantly decreases the release of cytokines that drive the inflammatory response." (PMID 34158856, 2021). "Interestingly, however, we observed that infection of VSV, IAV, ZIKV, or SeV did not lead to robust Ca2+ influx in either Trpv2fl/fl or Lyz2‐Cre;Trpv2fl/fl BMDCs, indicating that TRPV2 is not activated by these viruses." (PMID 36261399, 2022).
inflammation (3 papers, 2019 to 2020). Aberrant reaction of the microcirculation characterized by movement of fluid and leukocytes from the blood into extravascular tissues. "Among members of the TRPV subfamily, TRPV2 is expressed in many organs, such as the digestive tract, pancreas, and liver; furthermore, TRPV2 has been implicated in bowel inflammation, intestinal peristalsis, and the autocrine effects of insulin on pancreatic β-cells." (PMID 31690728, 2019).
brain diseases (2 papers, 2020 to 2021). "This interspecies difference from a gene expression point of view should be taken into consideration when modulators of TRPV2 or TRPV4 are investigated in rat models of brain disorders." (PMID 33262985, 2020).
cardiovascular diseases (2 papers, 2021 to 2024). "The latest reviews also indicate that an increasing number of studies are targeting TRPV1 and TRPV2 channels as therapeutic targets for cardiovascular diseases." (PMID 39742020, 2024). "Under pathological conditions, the activation of TRPV2 mediates abnormal Ca2+ influx, thus accelerating disease progression, which is considered as a therapeutic target for cardiovascular diseases." (PMID 34512785, 2021).
diseases of the nervous system (2 papers, 2018 to 2022). "Cannabidiol (CBD), a non-psychoactive compound and partial agonist of TRPV2 channels, is efficacious in many neurological disorders." (PMID 36292998, 2022).
hematological tumors (2 papers, 2014 to 2020). "A role of TRPV2 gene mutations in hematopoietic cancer development has been recently reported." (PMID 24709905, 2014). "The region 17p11.2, where the human TRPV2 gene maps, is an unstable chromosomal region characterized by a large number of low-copy repeats, which have been proven to mediate deletion and duplication in several genomic disorders and amplifications in hematological cancers." (PMID 24709905, 2014).
adenocarcinoma (1 paper, 2024). A common cancer characterized by the presence of malignant glandular cells. "TRPV2 signalling has previously been investigated using CBD in large human lung cell carcinoma and adenocarcinoma cell lines, but this study did not demonstrate expression of TRPV2 gene or protein." (PMID 38678280, 2024).
bacterial infection (1 paper, 2018). "To test the role of TRPV2 in human macrophage phagocytosis, we have first investigated the impact of bacterial infection on intracellular calcium homeostasis." (PMID 29523858, 2018). "In resting cells, TRPV2 is almost exclusively present in non-raft membranes (C + DSM, cytoplasm and detergent-soluble membrane) while bacterial infection increase significantly the level of TRPV2 detected in the enriched lipid rafts fraction (N + DRM, nuclei and detergent-resistant membranes)." (PMID 29523858, 2018).
TRPV2 also shares sentences with these, for which no sentence is quoted: multiple myeloma (5 papers); acute myocardial infarction (3); Alzheimer disease (2); bone disorder (2); esophageal cancer (2); metastatic cancer (2); skin disorder (2); acne (1); adenoid cystic carcinoma (1); amyotrophic lateral sclerosis (1); atherosclerosis (1); cardiac disease (1); cataract (1); cerebral infarction (1); channelopathies (1); cocaine use disorder (1); coronavirus disease 2019 (1); Crohn disease (1); cutaneous malignant melanoma (1); cystic fibrosis (1); dementia (1); diabetic retinopathy (1); emphysema (1); familial hemiplegic migraine types 2 (1); gastric tumors (1); Glucose intolerance (1); head and neck squamous cell carcinoma (1); hematological malignancies (1); Huntington disease (1); inflammatory bowel disease (1).
A further 20 diseases each share a sentence with TRPV2 in 1 paper.